CD4 (CD4 molecule)
Diseases named in the same sentence as CD4 in open-access papers (continued):
Sharing a sentence is not in itself a finding about the gene and the disease.
infection (continued). "Our data showed that breakthrough infection after different vaccination strategies disturbed the balance of cellular and humoral responses observed in primary SARS-CoV-2 infection but that the IFN-γ+CD4+ T-cell response correlates with the level of NAbs in MERS-CoV and H7N9 infection." (PMID 36543767, 2022). "Neither marker was increased in an infection on total CD4 T cells." (PMID 35851033, 2022). "Examining the overall infection scenario, we observed a significant reduction in HIV viral load log10 (p< 0.0001), a significant reduction in CD8+ T lymphocyte count (p< 0.0001), and an absolute increase in CD4+ T lymphocytes (p< 0.0001) after starting ART, over 24 months of observations." (PMID 35371095, 2022). "Thus, infection with low numbers of mycobacteria or leishmania parasites results in all the activated CD4 T cells belonging to the Th1 but not the Th2 subset." (PMID 35326834, 2022). "While these results can implicate TGF‐beta in altered CD4 Th subset differentiation over the course of infection, it does not determine whether the senescent environment or senescent cells themselves are the main drivers of this difference with age." (PMID 34962049, 2022). "Although we observed higher frequencies of TNF-α-positive peripheral blood CD4+ T cells at the time of the first challenge in vaccinated compared to control animals, T cell activation was not correlated with the number of SHIV challenges required for infection." (PMID 35196125, 2022). "In addition, mapping of M and S (spike protein) epitopes has shown that the highly expressed proteins during infection can be the first to be reacted by memory CD4+ T cells, which does not depend on the existence of class II epitopes." (PMID 36389144, 2022). "Therefore, we concluded that T lymphocyte subsets (CD3+ T cell, CD4+ T cell, and CD8+ T cell) could also be used to help monitor infection and assess the severity of bacterial infection." (PMID 36443747, 2022). "The host immune response against PJP involves complex interactions between CD4+ T cells, CD8+ T cells, alveolar macrophages, neutrophils, and soluble mediators (including leukotrienes, prostaglandins, and histamine) that can facilitate the clearance of infection." (PMID 36675844, 2022). "Although IFN-γ-independent CD4 T cell based control of M. tuberculosis infection has been demonstrated in vivo it is unclear whether CD4 T cells are capable of directly activating macrophages to control infection in the absence of IFN-γ." (PMID 35877763, 2022). "Non-healing wounds and infection may occur when CD4+T lymphocytes are lower than 200 cells/ul, leading to severe consequences." (PMID 36419079, 2022). "Surprisingly, cytometry analysis of TfhD3 cell subsets did not indicate a major impact of HIVYu2b infection on global TfhD3 cell proportion regarding their origin, suggesting that HIVYu2b infection did not preferentially orient any CD4+ T cell subsets toward TfhD3 at this time point." (PMID 34984326, 2022). "Interestingly, however, neither primary nor secondary infection with B. canis induced IFN-γ by CD4+ T lymphocytes in the spleen." (PMID 36032120, 2022). "More particularly, CD4+ T-cells lead immune responses against viral infections and CD8+ T-cells play a role of essential importance in the host’s defense against respiratory viruses, providing viral clearance and participating in the containment of secondary infections." (PMID 36289890, 2022). "However, cDC1 and cDC2 are somewhat plastic, particularly during infection and in other inflammatory conditions, where cDC2s for example can cross-present antigen to CD8+ T cells, and cDC1 are fully capable of presenting antigens to naïve CD4+ T cells." (PMID 36318581, 2022). "Since the CD4+ T cell response was similar in all four groups, the enhanced CD8+ T cell response seen in the saRNA participants has resulted in an increased ratio of antigen specific CD8+:CD4+ T cells, with the participants with previous infection having a ratio of >1." (PMID 36194628, 2022).
infection (continued). "However, as compared with uninfected control, this preferential infection does not result in a differential contribution of the distinct CD4+ T cell precursors to the overall TfhD3 cell pool." (PMID 34984326, 2022). "Interestingly, lack of CD4+ Trm formation after natural infection in mice appears to be reflected in humans, where the frequency of S. aureus reactive CD4+ Trm cells in lung tissue is also low." (PMID 35637249, 2022). "Among subjects receiving SARS-CoV2 vaccine injection, fewer CD8+ T cells producing interferon alpha and TNF-αwere found in the subjects without previous infection, and CD4+ cells with interleukin 2 expression were enriched as the major immune cells after vaccine injection." (PMID 36146454, 2022). "Regardless of infection status, upon vaccination, CD4+ T-Cells immediately rose to higher levels." (PMID 35955740, 2022). "H. pylori infection stimulates the recruitment and activation of immune cells such as Th1, in which Th1-dominant CD4+ T cells facilitate the inflammatory responses in gastric tissue by secreting IFN-γ, thereby playing a decisive role in controlling bacterial load and infection of H. pylori." (PMID 36190255, 2022). "Importantly, this was not due to preferential infection of a minor pre-existing population of CD69+ CD4+ T cells in blood." (PMID 35417711, 2022). "By contrast, resting CD4+ T cells were not infected (<1%) when cell-cell contact was prevented by separating the two cell populations by a transwell, a condition that allows for only cell-free infection." (PMID 35417711, 2022). "A detailed characterization of hepatic CD4+ and CD4- iNKT cells during early acute infection (day 3-14 pi; day 14 pi data not shown) and secondary infection (day 5 pri) as compared to controls showed stable number of these cells but substantial phenotypic heterogeneity as visualized on t-SNE plots." (PMID 36159876, 2022). "Furthermore, CBD-X extract downregulates the migration of CD4+ and CD8+ T cells in response to the chemoattractant SDF1 and thus may reduce the translocation of pro-inflammatory immune cells to the site of infection." (PMID 35651623, 2022). "Contrasting with the high mortalities of ducklings received PBS (100%), naïve CD4+ T cells (90%), and naïve CD8+ T cells (100%), transfer of Y- and PS-specific CD8+ T cells and Y-specific CD4+ T cells provided significant protection (100%, 85%, and 75%, respectively) against lethal infection." (PMID 36016955, 2022). "However, since disruption of the vaginal epithelium and related barrier breakage can aggravate HIV infection, tissue-resident CD4+ T cells may be more readily exposed to HIV-1, hereby triggering the infection." (PMID 35488095, 2022). "Indeed, SARS-CoV-2-induced CD4+ responses targeted 280 epitopes, 227 of which were not seen in unexposed donors, indicating that infection generates a new TCR repertoire." (PMID 35401519, 2022). "Thus, CD4+ T cells seem to have functional duality against Pneumocystis infection, first by helping B cells and CD8+ T cells to become protective differentiated memory cells and second by secreting proinflammatory cytokines to control the primary infection." (PMID 36177012, 2022). "However, even though CD4+ T cells are necessary for the development of functional memory CD8+ T cells, their requirement for the induction of a primary CD8+ T cell response following infection is less clear." (PMID 35764965, 2022). "However, when co-cultured with CD4+ T cells, the higher number of TNTs formed on DC surfaces was accompanied by a lower level of productive infection compared to co-cultures infected with nonopsonized HIV." (PMID 35204813, 2022). "This was only the case for rTregs, aTregs, and FoxP3+/CD4+ Tregs (not naive or memory populations), which could suggest a reduction in the blood counts of functionally active Tregs at the time of infection." (PMID 35406717, 2022).
infection (continued). "Moreover, IL-10 deficiency increased CD4+T cells and CD8+T cells but not macrophages in the liver of mice with infection." (PMID 36310865, 2022). "In SMs, CD4+ T cells, in particular central memory cells, did not upregulate CCR5 in response to in vitro stimulation, and the low CCR5 expression on central memory cells was associated with reduced susceptibility to infection." (PMID 35154162, 2022). "Notably, our patients with lower CD8 levels leading to a higher CD4/CD8 ratio did not present a more severe acute presentation of infection nor more inflammation at admission to the hospital when comparing to the other groups." (PMID 35814752, 2022). "Thus, our data suggest that while IL-27 is present in the lungs at 60 days of infections, differences in IL-27 production are not responsible for differences in CD4 T cell and IL-10 expression between young and old stressed mice." (PMID 36189368, 2022). "Moreover, tissue-resident CD4+ T cells with expression of CD32 have been reported in cervical samples in the absence of infection." (PMID 35616530, 2022). "The new finding of this study is the ability to predict the survival curve of the participating subjects by directly using the patient's age, route of infection, base CD4+ T lymphocyte count, and current WHO clinical stage without using clinically relevant laboratory test indicators." (PMID 36249590, 2022). "Nevertheless, even when the virus remains supressed, an important fraction of HIV-infected people will become immunodiscordant, as they fail to fully recover CD4+ counts and immune function especially those who failed to receive cART on the early stages of infection." (PMID 36569851, 2022). "Usually, once the number of CD4 per microliter of blood is less than 200, this means that the immune system is almost compromised and the human body can no longer effectively deal with many common infections." (PMID 35205215, 2022). "If so, it may provide interesting therapeutic strategies to diminish the effects of senescent cells and rescue CD4 T cell subset balance in the absence of infection." (PMID 36119079, 2022). "Furthermore, the decreased percentage of CD4+FoxP3+ T cells in the total lung lymphocyte population of IFT88 KO mice is not dependent on infection with Mabs and is apparent 3 months after deletion of the IFT88 gene (treatment with tamoxifen)." (PMID 36505420, 2022). "Additionally, treatment of DC/CD4+ T-cell co-cultures using AraC resulted in a decrease in infection, also using nonopsonized HIV." (PMID 35204813, 2022). "CD4 TEM cells are multifunctional in terms of cytokine secretion, express high levels of granzyme B and perforin, and may be important for protection against certain infections in vivo." (PMID 35894054, 2022). "However, that study only considered possible glycomic biomarkers, and was a small pilot that did not address the potentially confounding effects of age, sex, ethnicity, duration-on-ART, time of ART initiation (treatment at early vs. chronic stage of infection), or pre-ATI CD4 count." (PMID 34188039, 2021). "Next, we evaluated the latency reversal potential of the inhibitors in a more clinically relevant primary ex vivo infection latency model, in which CD4+ T cells are infected with a full-length non-replication-competent HIV-1 virus driving expression of a luciferase reporter." (PMID 34872356, 2021). "Infection with HR HPVs in the study and in the control groups was not correlated with CD4+ counts." (PMID 34208764, 2021). "A recent UK study found that only 6% (108/1,728) of patients with a CD4+ T-cell count at diagnosis may feasibly have had their CD4+ T-cell count taken during seroconversion (based upon the last negative test and tests for recently acquired infection)." (PMID 34414881, 2021).
infection (continued). "The percentages of CD21+ (B cells), WC1+ (γδ-T cells), CD4+ (helper T cells), CD8+ (cytotoxic T cells), CD14+ (monocytes/macrophages) and CD335+ (NK) cells were studied in the population of PBMC from G-NcSpain7, G-NcSpain1H and G-Control by flow cytometry at different times post-infection." (PMID 34239816, 2021). "As hypothesised, no T cell exhaustion was observed on CD4+ T cells at the late stage of the infection." (PMID 34215335, 2021). "However, the adaptive immune response is expected to be fully active within 3 weeks after the infection and SARS-CoV-2-specific CD4+ or CD8+ T cell responses, as well as high levels of neutralizing antibodies, are still detectable after 3–4 months post-infection." (PMID 34122423, 2021). "The CD4+ CM (Tcm) subset expanded with vaccination (P = 0.08) but not asymptomatic infection." (PMID 34935643, 2021). "Furthermore, surface levels of CD69 in CD4+ and CD8+ T cells were significantly lower in MLNs of mice infected with wild-type Salmonella compared to the steD mutant, indicating that this effect also occurs during natural infection." (PMID 34314469, 2021). "Notably, the cellular SIV RNA transcript was highly correlated with the levels of viral DNA in CD4+ T cells (p < 0.0001), which is consistent with the concept that viral DNA could be a template to yield HIV/SIV viral particles in early infection." (PMID 34960667, 2021). "Although a possible delay in CD4+ T cell recruitment to the site of infection was noted we could not detect any striking differences in the peripheral or CNS immune response between C56Bl/6 and SPARC−/− mice including T cell activation or cytokine production." (PMID 33633185, 2021). "However, the presence of proviral DNA does not necessarily indicate direct infection as this genetic material can result from the phagocytosis of debris from CD4+ T cells." (PMID 34572027, 2021). "Interestingly, the magnitude of the CD8+ Trm response was identical during the primary or the secondary infection, as opposed to the significant 2-fold increase response of CD4+ Trm at recall." (PMID 34564636, 2021). "Unlike activated CD4+ T cells that undergo rapid cell death during initial infection (due to rapid viral replication kinetics), viral replication kinetics are delayed in non-dividing myeloid cells, resulting in long-lived survival of infected macrophages and macrophage-like cells." (PMID 34790202, 2021). "Subsequent experimental studies have shown that when dendritic cells (DCs) are exposed to cell-free viruses, the infection spreads to CD4+ T cells, but they may not be the main players for the spread of the infection." (PMID 34439253, 2021). "In contrast, for H5N1, the combined-route and aerosol-exposed animals showed similar transient decreases in lymphocyte, T-cell, B-cell, and NK-cell numbers, acute monocyte activation, and increased Ki67 expression on CD8 T-cells, but not CD4 T-cells, on day 7–10 after infection." (PMID 33671829, 2021). "However, CD4-/- mice exhibit extremely low expression of CD40L in the CNS, suggesting that CD4+ T cells are the major cell population contributing to the expression of CD40L in the CNS post RSA59 infection." (PMID 34898656, 2021). "Whether the Treg compartment contains helminth-specific CD4+ T cells is largely unexplored due to a lack of tools to identify and track these cells during infection." (PMID 34237106, 2021). "A second patient was also diagnosed with PCP nine months after CAR-T-cell therapy and had an absolute lymphocyte count of 100 cells/μL (CD4+ count not available) at the time of infection; trimethoprim/sulfamethoxazole prophylaxis had been discontinued 3 months prior." (PMID 33672208, 2021). "The therapeutic efficacy of CD4+ T cells could be attributed to their ability to produce proinflammatory chemo- and cytokines that recruit and activate CD8+ T cells and innate immune cells, such as macrophages, to the site of the infection." (PMID 34439097, 2021).
infection (continued). "During the course of infection, an increase of CD4+ and CD8+ T lymphocytes counts during the fourth determination in the Good Prognosis Group, while in the Exitus Group, even if not statistically significant, we observed a decrease for both the CD4 and CD8 counts." (PMID 34439967, 2021). "B cells activated with CD40L and interleukin-4 (IL-4), which mimics signals received from activated CD4+ T cells, express the C-type lectin DC-specific intercellular adhesion molecule-3-grabbing nonintegrin (DC-SIGN) and can capture HIV-1, leading to trans infection of CD4+ T cells." (PMID 33688006, 2021). "During early infection, CSF HIV-1 may be predominantly sustained in CD4+ T-lymphocytes (T-tropic) with CSF HIV-1 populations genetically similar to those circulating in blood, presumably as a result of CD4+ T-cell traffic that carries both infected and uninfected target CD4+ T cells into the CNS." (PMID 33983973, 2021). "While other CD4+ and CD8+ memory T cell subsets, including transitional memory, terminal effector memory, and stem cell memory subsets, have been postulated to play a role in infection and cancer, their exact role in vaccine-elicited human immune responses is still unclear." (PMID 34758029, 2021). "The increase in the magnitude of the antibody response and MBC response in subjects with more severe infection could be due to increased CD4 T cell responses, although this was not directly tested in our study." (PMID 33468695, 2021). "In addition, patients with CMV reactivation showed a significant depression of circulating CD4+ T cell count and anti-CMV IgG levels during active infection, suggesting an impairment of immune system functions which are not able to properly face viral reactivation." (PMID 33981851, 2021). "Recognition of the infected B-cells by the BORF1- and BcLF1-specific CD4+ T-cell clones was not significantly different between day 0 and days 1, 2 or 3 post infection (p>0.05, RM one-way ANOVA with Geisser-Greenhouse correction and Dunnett’s multiple comparison test)." (PMID 34882759, 2021). "Thus, the H1-DDA/TDB-induced accumulation of activated CD4+ T cells during the early phase of infection with Mtb does not seem to be dependent on the expression of IL-23 and IL-17A." (PMID 34351501, 2021). "Therefore, it is conceivable that CD4 T cells are attracted by CXCL9/10 sources, being myeloid cells or SGECs in the vicinity of sites of infection, in order to facilitate the encounter of MCMV antigen-presenting cells and consequently to perform their effector functions, such as IFNγ production." (PMID 34959486, 2021). "Although cytotoxic CD8 T cells can control lytic infection in most organs, and despite a significant higher ratio in the SGs during MCMV infection, early studies defined this mucosal organ as an exception, where only virus-specific CD4 T cells are able to achieve control of lytic replication." (PMID 34959486, 2021). "However, CD4+ T cells primed and differentiated in an IL-10–enriched environment displayed reduced expression of CXCR3 and, because they did not migrate into the lung parenchyma, their ability to control infection was limited." (PMID 34554927, 2021). "2PTM studies visualized, for the first time, that while Leishmania-specific and non-specific CD4+ T cells both homed into infected skin of mice, Leishmania-specific T cells displayed reduced cell migration speeds and accumulated at the site of infection, based on their confined motility behaviors." (PMID 34093571, 2021). "However, total and proviral DNAs were still detectable in CD4+ T cells throughout SHIVC infection, regardless of treatment duration." (PMID 33568508, 2021). "We did not have access to clinical data on duration of infection or CD4 nadir for the HIV-infected ART treated participants so we could not evaluate the contribution of these parameters to the immune signature that we defined." (PMID 34635604, 2021).